LGALS3 (galectin 3)
Diseases named in the same sentence as LGALS3 in open-access papers (continued):
Sharing a sentence is not in itself a finding about the gene and the disease.
injury (13 papers, 2015 to 2024). Damage inflicted on the body as the direct or indirect result of an external force, with or without disruption of structural continuity. "Further, the genetic deletion of Galectin-3 reduced neuronal loss and administration of Galectin-3 antibody exerted neuroprotective effects in a preclinical model of traumatic brain injury together implicating a detrimental role of Galectin-3 after a brain injury." (PMID 31156388, 2019). "Rationale: Galectin-3 (Gal-3) drives fibrosis during chronic lung injury, however, its role in acute lung injury (ALI) remains unknown." (PMID 36003515, 2022). "Rationale: Galectin-3 (Gal-3) is an immune regulator and an important driver of fibrosis in chronic lung injury, however, its role in acute lung injury (ALI) remains unknown." (PMID 34526900, 2021). "The absence of galectin-3-positive cell clusters in thioacetamide-induced acute liver injury but their appearance in alpha-GalCer-induced acute liver injury may be due to the immune responses and underlying mechanisms that differ between NKT- and Kupffer cell-mediated liver injury." (PMID 38330036, 2024).
lung disease (13 papers, 2014 to 2025). "In Hermansky-Pudlak Syndrome lung disease, galectin-3 competes directly with TMEM219 to bind IL13RA2." (PMID 40663259, 2025). "The levels of galectin-3 were elevated in all of the studied lung diseases, with the highest expression of galectin-3 being observed in AME patients." (PMID 25033447, 2014). "Galectin-3, a member of the galectin family, plays a significant role in inflammation and fibrosis, and studies show that it is elevated in various conditions, including heart and lung diseases." (PMID 39941305, 2025). "Four potential biomarkers (alpha-1-antitrypsin, galectin-3, histone H4, semenogelin I) were identified and these may be useful in monitoring the inflammatory state of the lung diseases after NIMP exposure, although the markers do not appear to be specific for illnesses associated with NIMPs." (PMID 25033447, 2014).
multiple myeloma (13 papers, 2011 to 2024). "We evaluated galectin-3C, an N-terminally truncated form of galectin-3 that is thought to act as a dominant negative inhibitor, as a potential treatment for multiple myeloma (MM)." (PMID 21765917, 2011). "Galectin-3C is a dominant-negative form of Gal-3 and it is thought to act by blocking endogenous Gal-3 and may be a potential treatment for multiple myeloma." (PMID 36583779, 2023).
peripheral artery disease (13 papers, 2017 to 2024). "The features of SNPs linked to galectin-3 levels and investigates their potential correlations with peripheral artery disease." (PMID 38239874, 2023). "In addition, plasma galectin-3 concentrations were increased in patients with carotid atherosclerosis, and were independently associated with increased risk of cardiovascular mortality in patients with peripheral artery disease." (PMID 35414082, 2022). "Multiple clinical studies have found a significant correlation between elevated galectin-3 (Gal-3) in circulation and the diagnosis and severity of peripheral arterial disease (PAD)." (PMID 38239874, 2023). "In contrast to cardiac disease, information on galectin-3 in peripheral artery disease (PAD) is scarce." (PMID 28471381, 2017). "Galectin-3 distribution was altered in arteries from patients with the peripheral arterial disease; its expression was mainly localized in the middle media layer in peripheral arterial disease patients as compared to the outer adventitia layer in normal arteries." (PMID 36272642, 2022). "Besides, galectin-3 mediates thrombotic mechanisms in venous thrombosis and peripheral artery disease." (PMID 31080833, 2019). "Among them, galectin-3 levels and RhoA/Rho-associated protein kinase (ROCK)-related protein expression in peripheral blood were used in one study as therapeutic biomarkers to treat peripheral artery disease." (PMID 31080833, 2019). "The present study sought to characterize, in patients with peripheral artery disease (PAD), the localization of galectin-3 in arterial tissue, and to analyze the relationships between the circulating levels of galectin-3 and oxidative stress and inflammation." (PMID 28471381, 2017).
pituitary tumor (13 papers, 2011 to 2025). A benign or malignant neoplasm affecting the pituitary gland. "Methylation of the LGALS3 gene is one mechanism regulating the expression of Gal-3 in pituitary tumors." (PMID 40362297, 2025). "Our results are in line with this previous report but interestingly, suggested that galectin-3 can predict the outcome of PRL-secreting pituitary tumors in terms of post-surgical recurrence, response to DA therapy, and disease-free survival." (PMID 34322092, 2021). "If in mice, as in human pituitary tumors, Runx1 controls Galectin-3 protein expression, then Runx1 controls microglia morphology in vivo through Galectin-3 as our present findings suggest." (PMID 30930748, 2019). "First, that transcription factors Runx1 and Runx2 regulate Galectin-3 expression in human pituitary tumors." (PMID 30930748, 2019). "In this retrospective study, we investigated the prognostic role of galectin-3 and ERα, in predicting aggressiveness, post-surgical outcome, and responsiveness to DA therapy, in patients who underwent first line surgery for PRL-secreting pituitary tumors." (PMID 34322092, 2021). "While our cohort did not include confirmed pituitary tumors, the shared hormonal imbalances in PCOS and hyperprolactinemia suggest that similar mechanisms may contribute to elevated galectin-3 levels in these patients." (PMID 39958874, 2024).
brain injury (12 papers, 2017 to 2025). Acute and chronic (see also brain INJURIES, CHRONIC) injuries to the brain, including the cerebral hemispheres, CEREBELLUM, and brain STEM. "Interestingly, loss of galectin-3 attenuated the microglia-associated immune responses, thus improving disease outcome in mouse models of ischemic brain injury, AD and HD." (PMID 36115971, 2022). "In 100 patients with severe traumatic brain injury, plasma galectin-3 concentrations had a close relationship with inflammation, trauma severity and clinical outcomes." (PMID 29414883, 2018). "We decided to analyse the effect of brain trauma and galectin-3 gene deletion on the mRNA levels of NGF and BDNF." (PMID 28128358, 2017). "Overall, we conclude that galectin-3 acts as an alarmin under conditions of brain trauma, and induces a strong proinflammatory response, most likely through TLR4 activation, and might be involved also in the phagocytic response." (PMID 28128358, 2017). "Considering that the facilitation of M2 activation may be a promising strategy to promote tissue repair under conditions of brain trauma, pharmacological inhibition of galectin-3 deserves special attention." (PMID 28128358, 2017). "This analysis confirmed that microglia express galectin-3 under conditions of brain trauma." (PMID 28128358, 2017). "Our study demonstrates that galectin-3 could be working as an endogenous ligand for TLR4 24 h after brain trauma, at a time post-injury when galectin-3 mRNA and protein levels are high." (PMID 28128358, 2017). "Galectin-3 gene deletion decreased the number of “rod microglia” shortly after brain trauma, thus supporting a role of galectin-3 in the proinflammatory response to brain trauma." (PMID 28128358, 2017). "In line with this notion, a previous study using galectin-3-deficient primary adult microglia reported no overt phenotype under basal homeostatic conditions but a significant decrease in activation and proliferation in response to ischemic brain injury." (PMID 36115971, 2022). "We review the possible role and molecular mechanisms of inflammation as well as galectin-3 in brain injuries, especially focusing on EBI after SAH, and discuss galectin-3 as a potential new therapeutic or research target in post-SAH brain injuries." (PMID 29414883, 2018).
fungal infections (12 papers, 2009 to 2025). "Multiple studies have reported that viral, bacterial, and fungal infections are associated with elevated Galectin-3 concentrations, and that higher levels may correlate with infection severity and prognostic outcomes." (PMID 41234450, 2025). "Recent studies showed that galectin-3 knockout mice show an elevated number of neutrophils in the primary focus of infection and reduced fungal loads in the fungal pneumonia lesions and peritoneal cavity caused by fungal infection." (PMID 35437453, 2022). "With a better understanding of the molecular and cellular mechanism of galectin-3, it is pertinent to provide a new antifungal therapy for patients with fungal keratitis, and/or patients suffering from other fungal infectious diseases." (PMID 35437453, 2022). "Protective effects of galectin-3 deficiency in fungal keratitis proved the regulatory role of galectin-3 of neutrophil cell subtypes; thereby, our data hints at the importance of galectin-3 for innate immunity in fungal infection." (PMID 35437453, 2022). "Taken together, these data demonstrate that extracellular galectin-3 facilitates recruitment of neutrophils to the site of A. fumigatus infection, and reveals a novel role for galectin-3 in host defense against fungal infections." (PMID 32750085, 2020). "Intravital imaging studies confirmed that galectin-3 was required for normal neutrophil migration to the airspaces during fungal infection." (PMID 32750085, 2020). "Galectin-3 levels also increase in mouse and humans during fungal infection and play roles in reducing infection." (PMID 31781126, 2019). "The elevated galectin-3 expression might be an indicator of the inflammatory response against fungal infection." (PMID 35845133, 2022). "Our data suggested that galectin-3 might regulate the barrier function to prevent tissue damage from the beginning of the inflammatory disease in fungal infectious disease, which indicated the key role of galectin-3 in infectious disease in a larger field." (PMID 35437453, 2022). "The role of galectin-3 in host defense against fungal infections varies by species." (PMID 32750085, 2020). "The intermediate resistance to the fungal infection presented by C57BL/6 mice, associated with the development of a mixed type of immunity, was replaced with susceptibility to infection and a Th2-polarized immune response, in galectin-3-deficient (gal3−/−) mice." (PMID 19229338, 2009). "Because the LPS stimulus (TLR4 agonist) induces IL-10 production that is not controlled by galectin-3, we suppose that our observations may be peculiar to fungal infections." (PMID 19229338, 2009).
pancreatic ductal adenocarcinoma (12 papers, 2010 to 2026). An infiltrating adenocarcinoma that arises from the epithelial cells of the pancreas. "In another study decreased expression of galectin-3 was associated with advanced stage, tumor de-differentiation, and metastasis in ductal adenocarcinoma of the pancreas." (PMID 23658855, 2010). "Third, we investigated the expression profile of LGALS3 in pancreatic ductal adenocarcinoma (PDAC), integrating transcriptomic and immunohistochemical data to assess both RNA and protein levels." (PMID 41153387, 2025). "In this study, we sought to comprehensively investigate the transcriptomic and clinical significance of LGALS3 expression in cancer, with a particular focus on pancreatic ductal adenocarcinoma (PDAC)." (PMID 41153387, 2025). "Galectin-3 plays a multifaceted role in the pathogenesis and progression of pancreatic ductal adenocarcinoma, and its interaction with T lymphocytes represents a vital aspect of this complexity." (PMID 37892182, 2023). "Galectin-3 (Gal-3) plays a multifaceted role in the development, progression, and prognosis of pancreatic ductal adenocarcinoma (PDAC)." (PMID 37892182, 2023). "Galectin-3 is prominently involved in macrophage differentiation and activation within the context of pancreatic ductal adenocarcinoma." (PMID 37892182, 2023). "In conclusion, Galectin-3 (Gal-3) stands out as a pivotal and multifaceted molecule in the intricate tapestry of pancreatic ductal adenocarcinoma (PDAC) pathogenesis and progression." (PMID 37892182, 2023). "In addition, Galectin-3 released by pancreatic ductal adenocarcinoma cells after coculture with γδ T cells binds glycosylated γδ T cell surface receptor α3β1 integrin and contributes to inhibition of γδ T cell proliferation." (PMID 41477833, 2026). "One biological process in which this protein might be involved is the suppression of T cell-mediated lysis: Galectin-3 was shown to interact with LAG3 present on CD8 cells in pancreatic ductal adenocarcinoma." (PMID 34503258, 2021). "Authors concluded that galectin-3 expression might be a useful prognostic marker for survival in ductal adenocarcinoma of the pancreas." (PMID 23658855, 2010). "To evaluate the relevance of our cellular model findings in human cancer, we quantified MUC4 and LGALS3 mRNA levels in the cancerous and non-tumoral areas obtained from 10 human pancreatic ductal adenocarcinomas (PDAC)." (PMID 28262838, 2017).
primary biliary cholangitis (12 papers, 2016 to 2025). Primary biliary cholangitis (PBC) is a chronic and slowly progressive cholestatic liver disease of autoimmune etiology characterized by injury of the intrahepatic bile ducts that may eventually lead to liver failure. "The importance of galectin-3 in the activation of inflammasome and the consequent development of primary biliary cholangitis has been shown in two different animal models of the disease." (PMID 32707678, 2020). "The role of Galectin-3 in the specific binding to NLRP3, and inflammasome activation in models of primary biliary cholangitis has been recently described." (PMID 32707678, 2020). "In Novosphingobium aromaticivorans-induced primary biliary cholangitis (PBC), Galectin-3 was found to enhance NLRP3 inflammasome activation, thereby stimulating IL-1β production and worsening the progression of PBC." (PMID 37685870, 2023). "Further, Lgals3 ablation enhances liver steatosis, but attenuates inflammation and IL-33 dependant fibrosis in mouse model of non-alcoholic fatty liver disease (NAFLD), and enhances bile duct damage and liver fibrosis in xenobiotic induced primary biliary cholangitis (PBC)." (PMID 30800112, 2019).
amyloid (11 papers, 2019 to 2025). "Fourthly, the absence of longitudinal follow-up precluded assessing the predictive value of galectin-3 or presepsin for clinical outcomes, including disease severity or amyloidosis risk, to some extent." (PMID 41008774, 2025). "Another recently described, yet not characterised, player in the development of proteinuria and amyloidosis in FMF is high serum levels of galectin-3 (gal-3)." (PMID 37298536, 2023). "Galectin-3 (Gal-3) levels were found to be elevated in all amyloidosis groups." (PMID 37720240, 2023). "Despite the finding that percent Galectin-3 and MHC-II coverage in microglia is not different between treatment groups in the cortex using immunofluorescence, a clear dose-dependent increase in protein levels is observed in concentric rings around amyloid plaques for both proteins." (PMID 40830489, 2025).
angina pectoris (11 papers, 2018 to 2025). The symptom of paroxysmal pain consequent to MYOCARDIAL ISCHEMIA usually of distinctive character, location and radiation. "Specifically, Galectin 3 was an independent predictor of all-cause mortality, while Galectin 3 binding protein levels were independently associated with a higher risk of angina pectoris or reinfarction." (PMID 31035456, 2019). "Another study showed that patients with unstable angina had a higher level of galectin-3 than patients with stable angina, and a trend in correlation between serum galectin-3 levels and number of vessel disease in patients with CAD." (PMID 40747494, 2025). "Higher plasma levels of Galectin-3 have been shown in patients with unstable angina and were also correlated with the number of diseased coronary vessels." (PMID 31890043, 2019).
Chagas disease (11 papers, 2011 to 2024). A parasitic infection caused by Trypanosoma cruzi. "Immunohistochemical analysis revealed that the myocardial fibrotic areas correlated with higher expression of galectin-3, suggesting a role of this lectin as a putative marker of cardiac progression in Chagas disease." (PMID 35046919, 2021). "A widespread study using animal models and human settings underscored the involvement of galectin-3 in the development of heart disease at the chronic stage of Chagas disease." (PMID 35046919, 2021). "Galectin-3 null mice are viable under normal conditions and long lasting inflammatory responses, like Chagas' Disease and Schistosomiasis." (PMID 21573150, 2011). "However, IL-4 activity was abolished when the synthesis of endogenous galectin-3 was interrupted, clearly demonstrating the existence of a mechanism of cross-talk between IL-4 and galectin-3 in the context of acute Chagas disease." (PMID 35046919, 2021). "Pineda MA, Cuervo H, Fresno M, Soto M, Bonay P. Lack of galectin-3 prevents cardiac fibrosis and effective immune responses in a murine model of Trypanosoma cruzi infection." (PMID 33656072, 2021). "Plasma levels of galectin-3 also did not correlate with disease severity in Chagas disease patients." (PMID 29232393, 2017).
diabetic retinopathy (11 papers, 2007 to 2025). "For instance, higher galectin-3 levels have been related to an increased risk of diabetic retinopathy, but other research has reached the opposite conclusion." (PMID 32294902, 2020). "For instance, in animal models for glaucoma or diabetic retinopathy, the reduced expression of galectin-3 mediated a protective effect on retinal neurons, most likely via decreased neuroinflammation." (PMID 40806748, 2025). "Studies have found that Galectin-3 is related to the pathogenesis of diabetic retinopathy." (PMID 35083706, 2022). "Therefore, Galectin-3 seems to be a pivotal molecule triggering neurodegenerative, oxidative and inflammatory processes preceding vascular modifications in diabetic retinopathy, and its modulation might be a useful tool to prevent diabetic visual complications." (PMID 35083706, 2022).
Granuloma (11 papers, 2009 to 2023). A compact, organized collection of mature mononuclear phagocytes, which may be but is not necessarily accompanied by accessory features such as necrosis. "In a murine in vivo study, LDN antigens induced formation of Th2-associated granulomas in liver, possibly mediated by interaction with Lgals3 due to its high up-regulation in granulomas." (PMID 27058578, 2016). "In non-necrotic granulomas at 8 weeks p.i., localization of MSR1 or LGALS3 was consistent with that of PLIN2, suggesting that these two proteins are also the marker for FM in non-necrotic granulomas." (PMID 36237431, 2022). "Marked attenuation of the disease in Lgals3−/− and Gal-3 inhibitor, DAVANAT®, treated mice is manifested by the absence of bile duct damage, granulomas and fibrosis." (PMID 31231399, 2019).